APP (amyloid beta precursor protein)
Diseases named in the same sentence as APP in open-access papers (continued):
Sharing a sentence is not in itself a finding about the gene and the disease.
Cognitive impairment (continued). "Inhibition of γ-secretase diminishes Aβ formation, prevents Aβ aggregation, and reverses APP induced cognitive deficits in transgenic models of Aβ deposition." (PMID 26221415, 2015). "For example, knock out of interleukin-10 (IL-10), an anti-inflammatory cytokine, ameliorated cognitive impairment in APP/PS1 mice, consistent with enhanced IL-10 signaling in AD brains." (PMID 26074767, 2015). "Those mice harbor transgenes for human amyloid precursor protein (APP) bearing the Swedish mutation and a deletion mutant form of presenilin 1, and present increased Aβ production and cognitive deficits." (PMID 25617315, 2015). "Collectively, these results indicate that EPPS rescues hippocampus-dependent cognitive deficits when orally administered to aged, symptomatic APP/PS1 TG mice." (PMID 26646366, 2015). "Genetic deletion of AQP4 further exacerbated cognitive impairment in APP/PS1 mice, reflected by extended escape latency during the entire training periods." (PMID 26526066, 2015). "As an example, histone deacetylase inhibition increases expression of plasticity genes and ameliorates synaptic pathology and cognitive deficits in APP transgenic mice." (PMID 26379494, 2015). "TAT-APPsweBBP treatment reduced BACE1-mediated APP amyloidogenesis both in vitro and in 5XFAD mice, while also reducing cognitive impairments." (PMID 26091071, 2015). "Together these data suggest that derivatives of APP generated by β-secretase cleavage are responsible for cognitive deficits in FDDKI mice." (PMID 26405694, 2015). "Markers of synaptic activity have been used as surrogates for cognitive function as changes in these markers have been reported to correlate with cognitive deficits in several APP transgenic mouse models." (PMID 25153994, 2014). "We recently reported that chronic administration of berberine can significantly reduce Aβ pathology, gliosis and cognitive impairments in TgCRND8 mice via reducing the level of C-terminal fragments of APP and the level of phosphorylated APP." (PMID 24671102, 2014). "Cognitive impairment in the different groups was confirmed in the probe trail, which showed that the APP + EA group and the Con + EA group mice spent more time in the target quadrant than their non EA-treated counterparts (P < .05)." (PMID 24447795, 2014). "APP/PS1 transgenic mice have early onset time and intensive degree of Aβ despoition, following with neuronal loss and cognitive impairment." (PMID 24356899, 2014). "To assess the onset and progression of the cognitive impairments in the APP/PS1 KI mouse model, we have performed a comprehensive behavioral analysis across the lifespan of this model from 7 to 24 months old." (PMID 23705774, 2013). "We demonstrate accelerated Aβ aggregations in the APP/PS1 transgenic mice at six weeks post-TBI accompanied by expedited cognitive impairment in presymptomatic AD mice." (PMID 24223856, 2013). "One report describes cognitive deficits in 14-month-old APP/PS1 KI mice in a one-way active avoidance task." (PMID 23705774, 2013). "With regard to β-amyloid, similar to other commonly used models of AD such as the Tg2576 mouse and the 5xFAD mouse, in the APP/PS1 KI model the amyloid burden occurs prior to the onset of cognitive deficits." (PMID 23705774, 2013). "It has been reported that the oral administration of 3 mg/day of caffeine for two weeks was capable of improving cognitive impairment of 9.5 month old PS1/APP double transgenic mice." (PMID 23900282, 2013). "Other potential therapeutic targets such as elevated levels of oxidative stress and neuroinflammation also occur before the observable cognitive deficits in the APP/PS1 KI mouse model." (PMID 23705774, 2013). "For example, compared with other APP and PS1 AD mouse models, such as the APP/PS1 model and the APP + PS1 model, the onset of cognitive deficits in the APP/PS1 KI model appears to occur slightly later in life." (PMID 23705774, 2013).
Cognitive impairment (continued). "Several AD research groups have investigated PKC activation as a central regulator of APP processing, AD pathophysiology, and cognitive impairment." (PMID 22700373, 2012). "Recent studies have shown that Aβ generation, amyloid pathology, electrophysiological dysfunction, and cognitive deficits become abrogated when BACE1−/− mice are bred with APP transgenic mice." (PMID 22701746, 2012). "Numerous rodent studies have also demonstrated increased amyloid plaque deposition, cognitive impairment, and increased APP expression due to consumption of a high fat diet or under the conditions of diet-induced obesity (DIO)." (PMID 22912823, 2012). "The formation of these complexes promotes Aβ aggregation as an early event in the neurodegenerative cascade of AD and results in cognitive impairment in doubly transgenic mice expressing human amyloid precursor protein (APP) and human AChE." (PMID 21251245, 2011). "At this age, APP[V717I] animals show cognitive deficits, whereas amyloid plaque formation occurs several months later." (PMID 19196476, 2009). "It is most interesting to note that the APP [V717I] transgenic mice develop cognitive impairment, decreased long-term potentiation (LTP) and neophobia already at 3 month of age." (PMID 16212664, 2005). "Furthermore, the activation of reactive astrocytes through astrocyte-specific Nrf2 expression has been shown to decrease amyloid deposits and phosphorylated tau levels, ameliorating cognitive impairments in both APP/PS1 and Thy1-hTau P301S mouse models." (PMID 38733347, 2025). "However, metformin, which is known to increase insulin resistance, activated the transcription of both BACE-1 and APP, potentially explaining its unsatisfactory therapeutic effect on the cognitive impairment when used alone." (PMID 40076550, 2025). "Similarly, the CysLTR1 antagonist montelukast was recently found to alleviate asthma-exacerbated cognitive deficits in APP/PS1 mice." (PMID 40507859, 2025). "Our first hypothesis was directed to the evaluation of a mouse model of AD, namely, the APP/PSEN strain, which recapitulates several features of AD patients, including accelerated cognitive impairment, synaptic loss, and deposition of Aβ plaques in the brain." (PMID 39935382, 2025). "Building on the antioxidant and anti-inflammatory activities of safflower leaves, our previous study demonstrated that they can ameliorate cognitive impairment, decrease inflammatory factors, reduce lipid peroxidation products and suppress excessive astrocyte activation in APP/PS1 mice." (PMID 41462694, 2025). "In addition, high plasma APP level in patients with mild cognitive impairment predicts conversion to an overt AD." (PMID 40032716, 2025). "Of note, the meprin β overexpressing mice show mild cognitive impairments caused by amyloidogenic APP processing alongside hyperactivity and altered exploratory behavior seemingly independent of APP cleavage." (PMID 40135725, 2025). "Notably, neuropathology and cognitive impairment are both more severe and show an earlier onset in 5xFAD mice compared to APP/PS1 mice." (PMID 40346662, 2025). "Collectively, these findings indicate domain-specific and temporal characteristics of cognitive impairment in APP/PS1 mice, with spatial working memory deficits emerging earlier than recognition memory deficits, thereby providing behavioral evidence for staging the AD course." (PMID 41226060, 2025). "Moreover, in our previous research, KARI201 showed a significant improvement in learning and memory in the Morris water maze and fear-conditioning test, where the APP/PS1 mice with cognitive impairments were assessed." (PMID 39825014, 2025). "Our comprehensive evaluation of CBM588 demonstrates its remarkable potential to ameliorate cognitive impairment in APP/PS1 mice by modulating gut microbiota composition, upregulating short-chain fatty acids, particularly acetate, and mitigating neuroinflammation." (PMID 40621927, 2025).
Cognitive impairment (continued). "APP/PS1 mice developed significant cognitive deficits at 6 and 9 months." (PMID 41509946, 2025). "Importantly, activation of platelets in atrial fibrillation is correlated with cognitive impairment and the development of AD either directly by releasing amyloid precursor protein (APP) or indirectly by the release of pro‐inflammatory cytokines." (PMID 39828641, 2025). "Here we explored the effects of skeletal muscle Ctsb expression in an AD mouse model, expressing chimeric mouse/human Swedish amyloid precursor protein (APP) and presenilin delta 9 mutations (APP/PS1), that cause neuropathological changes such as amyloid plaques, gliosis, and cognitive deficits." (PMID 41047763, 2025). "Notably, pharmacological inhibition of AEP with compound #11, a small-molecule inhibitor, reduces Tau and APP cleavage, alleviating AD-related pathology and cognitive deficits in Tau P301S and 5XFAD mice." (PMID 40816999, 2025). "Furthermore, the improvement of cognitive deficits would originate not only from elevated ACh levels, but also from the blockade of Aβ-induced tau hyperphosphorylation, as was demonstrated in an APP/PS1 transgenic mice model." (PMID 41049759, 2025). "In addition, the deposition of Aβ, tau aggregates and cognitive impairments can be ameliorated by eliminating the gut microbiome in AD (APP/PS1, Tau/APOE4) mice through germ-free conditions or administration of antibiotics." (PMID 38414054, 2024). "Candida rugosa lipase (CRL) has been reported to increase the abundance of Acetatifactor and Clostridiales vadin BB60 in the gut, enhancing lipid hydrolysis and maintaining unsaturated fatty acid homeostasis, leading to reduced neuroinflammation and cognitive deficits in APP/PS1 mic." (PMID 38627829, 2024). "Additionally, Li and his team found that eriodictyol significantly improved cognitive deficits in amyloid precursor protein (APP)/presenilin 1 (PS1) mice." (PMID 39683630, 2024). "Bilberry anthocyanins (BA) lowered serum and brain LPS levels, increased SCFAs in feces, induced microglial phagocytosis of Aβ through the CD33/TREM2/TYROBP signaling pathway, alleviated hippocampal neuroinflammation, and reversed cognitive impairments in APP/PS1 mice." (PMID 38627829, 2024). "In addition to cleaving tau at N368, AEP can also cleave amyloid precursor protein (APP) to form APP 586–695, contributing to cognitive impairment and the pathogenesis of AD." (PMID 38114762, 2024). "Probio-M8 reduced Aβ plaque burden in the whole brain and could alleviate cognitive impairment in the APP/PS1 mouse." (PMID 38495110, 2024). "Some commonly deployed models for studying AD which are well-characterized for inducing neuropathological features and cognitive deficits characteristic of the disease include the mutant amyloid precursor protein and presenilin 1 (APP/PS1), Tg2576, and 5xFAD lines." (PMID 39027900, 2024). "Exercises improve cognitive deficits in the APP/PS1 transgenic mouse." (PMID 38457008, 2024). "This differential vulnerability in the disruption of NMDARs may be involved in the mechanisms causing abnormal network activity of the hippocampal circuit and cognitive impairment characteristic of APP/PS1 mice." (PMID 39175009, 2024). "The β-amyloid hypothesis posits that aberrant processing of APP forms neurotoxic β-amyloid aggregates, which lead to the cognitive impairments observed in AD." (PMID 39125997, 2024). "However, adeno associated virus (AAV) mediated hippocampal overexpression of CatB can improve cognitive impairment and reduce Aβ load in APP/PS1 mice." (PMID 39559895, 2024). "Various transgenic models for AD like APP/PS1 mice have been reported to exhibit cognitive defects reflected by impaired learning and memory, which is why they have served as a very useful model for studying AD pathology as well as developing anti-AD therapeutics." (PMID 39173945, 2024).
Cognitive impairment (continued). "Additionally, a recent animal study from our research group has shown that OCN can improve cognitive impairment in an AD transgenic mouse model (APP/PS1 mice)." (PMID 38769320, 2024). "Transgenic amyloid precursor protein (APP)-overexpressing mouse models of AD have shown amelioration of cognitive deficits following treatment with the pan-PDE4 inhibitors rolipram, roflumilast and FFPM, and with the PDE4D subtype-selective inhibitors GEBR-7b and GEBR-32a." (PMID 38521860, 2024). "It exerted neuroprotective effects against cognitive impairment in APP/PS1 double transgenic mice by regulating the metabolism of amyloid-β, enhancing the expression of neurotrophic factors, inhibiting neuroinflammation and elevating the expression of synapse structure related proteins." (PMID 39081953, 2024). "APP‐KI mice exhibit Aβ deposition at 2 months of age and cognitive impairment at 6 months of age." (PMID 37822109, 2023). "To detect the potential consequences of antibody therapy in APP/PS1 mice at different age, we performed A16 treatment in 3- and 5-month-old APP/PS1 mice before Aβ deposition development in brains, and 10-month-old APP/PS1 mice with significant plaque load, synapse loss and cognitive impairments." (PMID 36693826, 2023). "As Mettl1-deficency mice exhibited decreased neurogenesis and cognitive impairment, we next investigated whether forced expression of Mettl1 improved hippocampal neurogenesis and cognitive function in APP/PS1 mice." (PMID 37779199, 2023). "Moreover, silencing METTL3 by sh-METTL3 AAV ameliorated synaptic and cognitive impairments in 6-month-old APP/PS1 mice." (PMID 38012808, 2023). "In conclusion, we confirmed that HC alleviated oxidative stress and cognitive impairment in APP/PS1 mice by activating Nrf2 signaling and regulating the gut microbiota, thus playing an anti-AD role and suggesting that HC is a promising potential treatment for AD." (PMID 37686830, 2023). "Thus NF-α1/CPE gene therapy targets many regulatory components to prevent cognitive deficits in 3xTg-AD mice and has implications as a new therapy to prevent AD progression by promoting cell survival, inhibiting APP overexpression and tau hyperphosphorylation." (PMID 37369719, 2023). "The purpose of the study was to determine whether KXS might ameliorate cognitive deficits in APP/PS1 mice and to evaluate its neuroprotective mechanism." (PMID 36918872, 2023). "Additionally, forced expression of Mettl1 remarkably ameliorated cognitive impairment in APP/PS1 mice." (PMID 37779199, 2023). "At this age, amyloid plaques and cognitive impairments can be clearly identified in APP/PS1 mice." (PMID 36902054, 2023). "It has been shown up until now, that ovocystatin has a beneficial impact on cognitive function in young rats, and might prevent aging-related cognitive impairment in older animals and reduce memory decline in APP/PS1 mice model." (PMID 36982505, 2023). "Our research shows that increasing the polarization of hypothalamic Aqp4 through mitochondrial energy supply may be an important target for moxibustion to improve cognitive impairment in APP/PS1 mice." (PMID 36819717, 2023). "Therefore, we postulated that KXS-H alleviate mitochondrial dysfunction and thereby avoid cognitive impairment in APP/PS1 mice." (PMID 36918872, 2023). "The results indicated that KXS protected APP/PS1 mice against cognitive impairments." (PMID 36918872, 2023). "Given the critical role of GluA1 in synaptic plasticity, a paired decrease in synaptic content of GluA1 and GluN2A may render APP/PS1 mice more vulnerable to develop cognitive impairments." (PMID 37980670, 2023). "However, 1-week exposure to menthol per month, during these 6 months was able to significantly prevent the cognitive impairment observed in the APP/PS1 mice treated with water vapor reaching freezing values similar to wild-type control mice." (PMID 37187754, 2023). "APP/IR‐dKI mice exhibited cognitive impairment at an earlier age than APP‐KI mice." (PMID 37822109, 2023).
Cognitive impairment (continued). "Consistently, Aβ-targeting antibodies, but not their Fab fragments, significantly induced acute microglial synapse removal and rapidly exacerbated cognitive deficits and neuroinflammation in APP/PS1 mice post-treatment, whereas the memory impairments in mice were gradually rescued thereafter." (PMID 36693826, 2023). "Advanced-stage APP/PS1 mice had marked cognitive impairments relative to early-stage mice." (PMID 37433857, 2023). "Together, these findings may contribute to an accelerated cognitive impairment in APP/PS1 mice by ELS and potentially lead to ELS-enhanced vulnerability to AD-pathology in late adulthood." (PMID 37980670, 2023). "In this study, first we confirmed that 9-10 months old APP/PS1 mice (carrying transgenes for both APP bearing the Swedish mutation and PSEN1 containing an L166P mutation, both under the control of the Thy1 promoter) display short-term memory and cognitive deficits." (PMID 36937050, 2023). "Secondly, we only explored the metabolomic changes in the fecal and serum samples before and after cognitive impairment in APP/PS1 mice; however, combined multi-site and multi-omics studies can more accurately determine the regulatory networks associated with the development of cognitive decline." (PMID 37095548, 2023). "Thus, Neu3 overexpression aggravated cognitive impairment in APP/PS1 mice, suggesting that increased GM1 levels accelerate the progression of AD." (PMID 37759382, 2023). "As a result, rhein could permeate into the brain, reduce Aβ deposits and neuroinflammation, and finally ameliorate cognitive impairment in APP/PS1 mice." (PMID 35360200, 2022). "In addition, the amelioration of cognitive impairment in APP/PS1 mice by exercise training was also related to Navβ2 regulation." (PMID 36406589, 2022). "Specifically, Barnes maze tests revealed that the M489V variant of PKCα alone, without the presence of APP, was able to induce cognitive impairment." (PMID 36418293, 2022). "Interestingly, microglia from APP/PS1 mice show an increase in the murine FPR1 and FPR2, and treatment of APP/PS1 mice with a competitive FPR inhibitor ameliorated cognitive impairment, reduced plaque load, and lessened microglial reactivity." (PMID 36359817, 2022). "First, the onset of cognitive deficit in the 6xTg mice is at 2 months of age, suggesting that the 6xTg mice undergo the earliest cognitive decline compared to the other major mouse models of AD (5xFAD, 3xTg-AD, APP/PS1)." (PMID 35676711, 2022). "However, 8 weeks of RH treatment dramatically accelerated the progression of AD-type pathologies and cognitive impairment in APP/PS1-DM mice, indicating that RH can promote AD progression." (PMID 35077394, 2022). "In this study, we employed APP/PS1 mice to further investigate whether TA ameliorates cognitive impairment and inhibits the expression of Aβ and apoptosis protein in vivo." (PMID 35918778, 2022). "To investigate whether Xn preventively and/or therapeutically relieves cognitive deficits, we tested 2-month- and 6-month-old transgenic APP/PS1 mice and their wild-type littermates with Xn or corn oil by oral gavage every other day for 90 days." (PMID 35209070, 2022). "In addition, LH has also been confirmed to be involved in APP metabolism and Aβ plaque formation in the hippocampus, and reducing LH can improve cognitive impairment." (PMID 36213283, 2022). "Cognitive impairment has been validated for APP/PS1 mice as early as 9 months of age." (PMID 35453459, 2022). "Studies conducted on APP/PS1 mice, a model of AD, revealed that FoA deficiency intensify Aβ generation improving APP and beta-site amyloid precursor protein cleaving enzyme 1 (BACE1) expression, suggesting that folic acid deficiency exacerbates cognitive impairment." (PMID 35213966, 2022).